DAOA-AS1 (DAOA antisense RNA 1)
Synonyms: G30; DAOA-AS; DAOAAS
Gene: Long non-coding RNA gene on chromosome 13 (105,459,055 to 105,505,681, reverse strand). Ensembl gene ENSG00000232307.
Diseases named in the same sentence as DAOA-AS1 in open-access papers:
DAOA-AS1 is named in the same sentence as 9 diseases in open-access papers, as found by Europe PMC text mining. Sharing a sentence is not in itself a finding about the gene and the disease. The quoted sentences say what the papers report.
bipolar disorder (1 paper, 2022). A disorder of the brain that causes unusual shifts in mood, energy, activity levels and the ability to carry out day-to-day tasks. "Finally, the DAOA-AS1 gene is extracted for bipolar disorder as reported in90." (PMID 35705654, 2022).
DAOA-AS1 also shares sentences with these, for which no sentence is quoted: chronic fatigue syndrome (1 paper); cutaneous T-cell lymphoma (1); generalized epilepsy (1); male infertility (1); panic disorder (1); personality disorder (1); Pseudoxanthoma elasticum (1); Sezary syndrome (1).